MUC1 (mucin 1, cell surface associated)
Diseases named in the same sentence as MUC1 in open-access papers (continued):
Sharing a sentence is not in itself a finding about the gene and the disease.
breast carcinoma (continued). "MUC1 and vascular endothelial growth factor (VEGF) expression in human breast cancer are highly correlated, and it has been demonstrated that MUC1 expression promotes angiogenesis in human breast cancer both in vivo and in vitro." (PMID 34207342, 2021). "Taken together, MUC1, MUC15, MUC14 and MUC18 were identified as the most potential MUC members in breast cancer and were selected for subsequent analysis." (PMID 34828282, 2021). "Considering the expression change of MUC1, MUC15, MUC14 and MUC18 in breast cancer, we intended to ascertain if they possessed promising predictive roles for diagnosis and prognosis of breast cancer." (PMID 34828282, 2021). "Recently, we examined the multi-targeted potential of a monoclonal antibody against mucin 1 (MUC1) and a novel octahydropyrazino[2,1-a:5,4-a′]diisoquinoline derivative (OM-86II) in estrogen receptor-positive MCF-7 human breast cancer cells." (PMID 33918514, 2021). "The AdnaTest® assay is an RT-PCR based test for detecting cancer-specific mRNA markers, e.g., GA733-2, MUC1, and HER2 for breast cancer, after immunomagnetic enrichment of tumor cells with MUC1 and EpCAM antibodies." (PMID 32992445, 2020). "With the overexpression of NUDT5, tumor-relevant proteins MUC1 which was known to upregulate the EMT drivers’ expression, was also enriched in breast cancer cell." (PMID 32518727, 2020). "A previous study reports that GALNT6 O-glycosylates and stabilizes Mucin 1 (MUC1), regulating the EMT process in breast cancer cells." (PMID 32393740, 2020). "Previous studies have reported that MUC1 and FN are classic mucin-type O-glycosylation substrates of GALNT6 which can promote the malignant phenotype of breast cancer cells." (PMID 32559179, 2020). "Recent evidence suggests that suppression of MUC1, in turn, down‐regulates the anti‐apoptotic MCL1 protein in breast cancer cells." (PMID 32720467, 2020). "In an in vivo mouse mammary tumour model, anti-MUC1 or anti-Her2 (C6MH3-B1) IgE therapy reduced mucin-1+ (MUC1+) or Her2+ tumour outgrowth, respectively, and improved the survival of tumour-bearing hFcεRI transgenic mice." (PMID 33081206, 2020). "MUC1 overexpression is reportedly induced by interferon γ (IFN-γ) in ovarian and breast cancer cell lines." (PMID 31514468, 2019). "We sought to study the effects of a MUC1 vaccine, alone and in combination with several different COX inhibitors, on breast cancer progression in an immunocompetent mouse model." (PMID 31693710, 2019). "The proposed ECL imaging platform shows excellent performance for sensitive and specific quantification of cell surface MUC1 and HER2 with an LOD in the pg mL–1 level, and can be used for screening of breast cancer cells." (PMID 31391903, 2019). "We have previously demonstrated that MUC1-EGFR complexes are capable of localizing around and entering the nucleus, acting as a co-transcriptional activator of genes upregulated in breast cancer, such as cyclin D1." (PMID 29464085, 2018). "We have previously demonstrated via the WAP-TGFα transgenic mouse model that EGFR is colocalized with the oncogenic adaptor protein MUC1 in hyperplastic and tumor tissues and EGFR-driven breast cancer is largely MUC1-dependent." (PMID 29464085, 2018). "The combined effects of a monoclonal antibody against MUC1 used together with a dinuclear platinum(II) complex showed high anti-proliferative properties and strong cytotoxic activity in MCF-7 and MDA-MB-231 breast cancer cell lines." (PMID 29862867, 2018). "We began by evaluating the colocalization of MUC1 and EGFR with EEA1, a marker of the early endosome in both BT20 and MDA-MB-468 breast cancer cells." (PMID 29464085, 2018).
breast carcinoma (continued). "Targets used in monovalent vaccines for breast cancer include HER2, mucin 1 (MUC1), and carcinoembryonic antigen (CEA)." (PMID 29881518, 2018). "25%–30% breast cancer patients exhibit HER2 overexpression and almost all breast cancers show MUC1 expression." (PMID 28085094, 2017). "In conclusion, our study evidences a vital role for MUC1 in TNBC and a potential mechanism by which MUC1 contributes to the metabolic process involved breast cancer." (PMID 28464016, 2017). "The AdnaTest Breast Cancer assay identified 15 of 34 CTC positive patients (44%) at BL (PCR based detection of EpCAM, HER2 or MUC1 transcript ≥ 15ng/ul)." (PMID 28489591, 2017). "Quantitation of MUC1-ARF protein in nuclear and cytoplasmic compartments demonstrated MUC1-ARF protein in nuclear extracts prepared from human T47D breast cancer cells while cytoplasmic extracts displayed much lower levels." (PMID 27768738, 2016). "In breast cancer, overexpression of N-acetylgalactosaminyltransferase (GALNT6) contributes to increased proliferation possibly through stabilization of MUC1 protein." (PMID 27754373, 2016). "These peptides elicited robust lytic CTLs from normal donors, as well as breast cancer patients that were effective in killing MCF-7 breast cancer cells (HLA-A*0201+, MUC1+) at high efficiency." (PMID 27367740, 2016). "In contrast to localization of MUC1-TM to the cell surface, MUC1-ARF localizes to the cell nucleus, as observed in normal kidney and pancreas as well as in breast cancer tissues." (PMID 27768738, 2016). "Overexpression of STn-MUC1 forms, induced in vitro by transfection of ST6GalNAc1, significantly enhanced the binding of MUC1 and CIN85 in breast cancer cells." (PMID 27754373, 2016). "Following reaction of each of the three antibodies with mouse mammary tumor cells stably transfected with and expressing human MUC1 DNA (DA3-MUC1) a strong nuclear signal was seen, as well as a lower level signal in the cell cytoplasm (DA3-MUC1)." (PMID 27768738, 2016). "Mucin-1 (MUC1, CD227), more widely known as CA15-3, has evolved to be one of the best validated breast cancer serum tumour markers." (PMID 25986064, 2015). "We have previously shown that the tumor form of MUC1 and CIN85 are expressed at significantly higher levels in early and advanced stage of human breast cancer compared with normal epithelium." (PMID 25675408, 2015). "The T cells stimulated with HSP70.PC-Fc lysed the autologous breast cancer cells (HLA A11+) with the greatest efficacy followed by lysis of SKBR3 that shared tumor antigens and HLA elements (HLA A11+/A2-, MUC1+, HER2+)." (PMID 25961716, 2015). "Effector T cells (HLA A2+ from Patient 1 or Patient 2) stimulated with HSP70.PC-Fc lysed the autologous breast cancer cells (HLA A2+) and to a lesser extent, the MCF7 breast tumor cells (HLA A2+, MUC1+, HER2+)." (PMID 25961716, 2015). "Clinically, detection of circulating serum mucin levels is an FDA-approved prognostic factor in the treatment of breast cancer and phase III clinical trials evaluating MUC1 based immunotherapies are underway." (PMID 26147830, 2015). "MUC-1 mucin from breast cancer cell lines (MCF-7, BT-20, and T47D) has simpler glycosylation pattern and fewer carbohydrate chains than MUC-1 from normal breast epithelial cells (MMSV1-1, MTSV1-7, and HB-2) with higher ratio of GlcN/GalN." (PMID 26783462, 2015). "In particular, we showed that underglycosylated form of MUC1 and CIN85 co-localize on invadopodia structures regulating migration and invasion of breast cancer cells." (PMID 25675408, 2015). "One such factor turned out to be mucin-1 (MUC1), an oncogenic glycoprotein that has been shown to be expressed in a large fraction of breast cancer samples." (PMID 25472813, 2015). "An important goal of targeted therapy appears to be a transmembrane glycoprotein type I—mucin 1 (MUC1), which is overexpressed in tumors of epithelial origin, especially in breast cancer." (PMID 26112902, 2015).
breast carcinoma (continued). "In 2011, autoantibodies to several glycopeptides of MUC1, the protein recognized by the cancer antigens CA15-3 and CA27.29, were found to discriminate sera drawn from breast cancer patients at diagnosis from benign and healthy controls." (PMID 26565788, 2015). "In breast cancer cells, FGF1 plays similar role in the mitochondrial localization of MUC1 using similar molecular mechanism." (PMID 25261375, 2014). "Gain of 1q in cancer, specifically in breast cancer has previously been described but is impressively evidenced in this study by frequent co-amplification of the SYK-regulated SPRR1A, SPRR1B, MUC1, RAB25, and ADAM15, genes located within chromosome 1q." (PMID 24523870, 2014). "The list of genes up-regulated in both neoplasia and breast cancer includes well-known Cancer Gene Census genes such as ERRB2, GATA3, and MUC1, among others." (PMID 24887547, 2014). "The dinuclear platinum(II) complex (Pt12) has been synthesized, and its cytotoxicity with anti-MUC1 has been tested in both MCF-7 and MDA-MB-231 breast cancer cells." (PMID 24639126, 2014). "Elevated NFkB binding activity has been observed in both primary human breast cancer tissues and breast cancer cell lines, and contributes to the activation of CYCLIN D1, c-MYC, and MUC1." (PMID 24243820, 2013). "The CA 15-3 test is used to quantify a sialylated O-glycosylation epitope on mucin 1 (MUC1), and is used for prognosis and monitoring of treatment for breast cancer." (PMID 23390961, 2013). "Multiple tumor biomarkers have been reported in breast cancer including carcinoembryonic antigen (CEA), mucin 1 (MUC1) and CA 15-3." (PMID 23451156, 2013). "The binding of NM23-H1 to MUC1* was reported to result in dimerization of MUC1*, and subsequent activation of the MAPK pathway to increase proliferation of the breast cancer cell line T47D." (PMID 21941554, 2012). "Very recent data indeed indicate that the MUC1 3’-UTR is directly regulated by miR-125b, miR-145 and miR-1226 in human breast cancer cell line." (PMID 24281201, 2010). "MUC1/IgG/CIC OD mean values were 0.763 ± 0.276; 0.758 ± 0.251 and 0.831 ± 0.359 for breast cancer, benign and normal samples, respectively." (PMID 19715603, 2009). "Two breast cancer cell lines, T47D and MDA-MB-231, were characterized for their expression of MUC-1." (PMID 19635153, 2009). "MUC1-positive breast cancer cells were double stained with VU4H5 that binds to tandem repeats units in the high molecular weight fragment and Anti-MUC1* that binds to the low molecular weight, membrane-bound cleavage product, MUC1*." (PMID 18446242, 2008). "We identified a panel of tumor-specific antibodies from the described libraries; these antibodies were reactive with ED-B domain, MUC1, CEA and MCF7 breast carcinoma cells used in the respective selections." (PMID 17945015, 2007). "These libraries and one from peripheral blood lymphocytes of a single breast cancer patient were panned against three purified surface tumor antigens, such as CEA, MUC1 and ED-B domain, and against intact MCF7 breast carcinoma cells." (PMID 17945015, 2007). "Abnormal expression of the mucins MUC1 and MUC4 has been observed in tumor cells of various tissues, including lung, colon, pancreatic, ovarian, and breast cancers." (PMID 18053197, 2007). "In breast cancer, the tumor antigen CA15-3 is expressed on MUC1, which is aberrantly expressed in more than 90% of breast carcinomas and appears to promote invasion." (PMID 18053197, 2007). "GATA3 knockdown assays led to a significant decrease in MUC1 protein expression in MCF7 breast cancer cells, strongly suggesting an involvement of GATA3 in the modulation of MUC1 expression." (PMID 17078870, 2006).
breast carcinoma (continued). "In mouse breast carcinoma DA3 cells transiently transfected with plasmid Dpr, MUC1/SEC was the only human MUC1 isoform observed (lane – 1)." (PMID 17083744, 2006). "Overall, these studies showed a consistently statistically significant correlation between GATA3 and MUC1 expression at the mRNA and protein levels by SAGE profiling (p = 0.002), real-time RT-PCR (p < 0.0001), and TMA (p = 0.01) in breast carcinomas." (PMID 17078870, 2006). "Similarly, though MUC1 drives mammary oncogenesis in its own right and facilitates tumorigenesis driven by other oncogenes, Muc1 is selectively down-regulated in c-neu-induced mouse mammary tumors, indicating that the context of oncogenic signaling is vital to understanding the function of MUC1." (PMID 16846534, 2006). "Contrary to our expectations, we found that irradiated basal-like breast cancer (BLBC) tumors shifted their epithelial/mesenchymal hybrid state toward a stronger epithelial gene expression program, ultimately driving MUC1 (Mucin 1) expression as a key mediator of cell survival following RT." (PMID 41999194, 2026). "EVsderived from breast cancer cells contain elevated levels of proteinssuch as HER2, EGFR, CA 125, CA15–3, PSMA, EpCAM, and MUC1,which are commonly found in breast cancer patients and may serve asEV-derived biomarkers." (PMID 40720603, 2025). "MUC1 expression was detected in most breast cancer tissues, while no expression was detected in normal breast tissues." (PMID 41471303, 2025). "As an example, Mucin 1 (MUC1) is a clinically significant tumor-associated antigen in breast cancer vaccine development, as it is overexpressed in most breast cancers and absent in normal tissue." (PMID 41295524, 2025). "The anti-MUC1-C ADC was active against MUC1-positive, but not MUC1-negative, TNBC breast cancer cells and nontoxic in human MUC1-transgenic (MUC1.Tg) mice." (PMID 40287441, 2025). "Upcoming studies of CAR-T in breast cancer include a phase I/II (NCT04020575) study targeting metastatic breast cancer expressing Muc1 growth factor receptor, called Muc1*, and a phase I study (NCT02706392) of CAR-T in liquid and solid malignancies expressing ROR1." (PMID 39722028, 2024). "The combination of one MUC-1 marker and CEA is used in breast cancer patients." (PMID 38672729, 2024). "Examples of TAAs in breast cancer include HER2, Muc-1, and CEA." (PMID 39722028, 2024). "The aim of this study is to measure the level of degradation products of MUC1, including CA 15-3, CA 27.29, and MCA, in the saliva of breast cancer patients and to describe the biochemical processes that influence their expression and the regulation of their biological functions." (PMID 39456554, 2024). "Objectives: to measure the level of degradation products of MUC1, including CA 15-3, CA 27.29, and MCA, in the saliva of breast cancer patients and to describe the biochemical processes that influence their expression and the regulation of their biological functions." (PMID 39456554, 2024). "The VFA was made to quantitatively profile serological exosomes from different breast cancer subtypes through the detection of exosomal surface proteins carcinoembryonic antigen (CEA), human epidermal growth factor receptor 2 (HER2), and Mucin 1 (MUC1)." (PMID 38811455, 2024). "Furthermore, in breast cancer diagnostics, only a limited number of serum-based biomarkers have received FDA approval for monitoring advanced or recurrent cases, namely MUC-1 (CA27.29 and CA15-3) and carcinoembryonic antigen (CEA)." (PMID 38542382, 2024). "Hence, MUC1 was silenced in mouse (PyMT41c) and human (MCF7 and T47D) mammary cancer cells, and spheroids were counted in the presence of a medium conditioned by mast cells." (PMID 39349458, 2024). "Likewise, MUC1-targeting DT-conjugated AS1411 aptamer nanocarrier of Dox can reduce the drug cytotoxicity and resistance, whereby improving the drug efficacy in breast cancer." (PMID 38087297, 2023).
breast carcinoma (continued). "Previous studies on cancer biomarkers for breast cancer have demonstrated that their low sensitivity and specificity prevent from the use of serum markers such as the MUC-1 mucin glycoproteins (CA 15.3, BR 27.29) and carcinoembryonic antigen (CEA) for the diagnosis of early breast cancer." (PMID 37207139, 2023). "Currently known oncodrivers in breast cancer are EGFR, HER2, HER3, MET, and mucin-1 (MUC1)." (PMID 36900322, 2023). "Antibodies from sera from Qβ-MUC1 immunized mice recognized tissues from human breast cancer but not from normal human breasts." (PMID 36851313, 2023). "Furthermore, miR-145 inhibits breast cancer cell motility and invasiveness by negatively regulating the junctional cell adhesion molecule (JAM-A), fascin and MUC1." (PMID 37513415, 2023). "The soluble form of MUC-1 in peripheral blood is called CA15-3, extremely expressing in human mammary malignancies, and is one of the best known and most broadly used serum tumor markers in women with breast cancer." (PMID 35000604, 2022). "Our results suggested that MUC1/ATAD3A/Pink1 axis-mediated mitophagy improved cancer cell proliferation, mammosphere formation, and tumor growth, suggesting a tumor-promoting role in breast cancers." (PMID 36289190, 2022). "In human breast cancer, cathepsin D (CTSD), IL4 receptor (IL4R), mucin-1 (MUC1, CD227), and serine protease 3 (PRSS3) may serve as valuable biomarkers for the diagnosis and treatment of breast cancer." (PMID 35787690, 2022). "However, there are cancer vaccines using MUC1 glycopeptides that bind to MHC-I, inducing a cytotoxic CD8 response observed in healthy donors as well as in breast cancer patients." (PMID 36291752, 2022). "Biomarkers such as carcinoembryonic antigen (CEA), vascular endothelial growth factor (VEGF165), MUC1, platelet-derived growth factor (PDGF), and human epidermal growth factor receptor 2, play a critical role in the diagnosis of breast cancer in the early stages." (PMID 35457828, 2022). "MUC1 soluble form, also known as CA15-3, is widely used as a serum marker for breast cancer." (PMID 36430448, 2022). "MUC1 is an important breast cancer biomarker that often exhibits a nonpolar distribution in tumor cells and thus has become a target of tumor bioimmunotherapy." (PMID 34266419, 2021). "Transmembrane glycoprotein mucin 1 (MUC1), nucleoli, and epidermal growth factor receptor (EGFR) are frequently used markers in the electrochemical detection of breast cancer cells, which have been proven to be highly overexpressed on the surfaces of breast cancer cells." (PMID 34360949, 2021). "A glycopeptide vaccine STn-KLH based on conjugated MUC1 glycopeptides and glycoforms of Tn and S-Tn induced antibody responses in mice but failed to improve OS for breast cancer patients." (PMID 34065557, 2021). "The biomarkers with the most evidence as highlighted in this paper which may have prognostic implications on breast cancer in older women include and are under reported in the current literature include: BCL2, cyclin E, EGFR, LKB1, MUC1 and CKs." (PMID 34165702, 2021). "As MUC1-ST supported the differentiation of monocytes to TAM-like macrophages, this glycoform is commonly expressed in breast cancers and correlated with macrophages present in the stroma around the cancer nests, we wished to further explore the relationship between MUC1-ST and TAMS." (PMID 33149188, 2020). "Here, we show that MUC1-ST is expressed by the majority of breast cancers and, acting in serum-free medium without the addition of cytokines, has the ability to induce the differentiation of monocytes to macrophages and to promote their viability." (PMID 33149188, 2020). "Despite this variation, studies of MUC1 in African breast cancer have been sparse, and currently, no single such study has been done here in Ghana." (PMID 32377198, 2020). "MUC1‐targeted SERS NPs were co‐injected with nonspecific SERS NPs with different spectral signatures in a breast cancer xenograft mouse models." (PMID 33304747, 2020).